MIR3188 (microRNA 3188)
Synonyms: hsa-mir-3188; mir-3188
Gene: MicroRNA gene on chromosome 19 (18,282,077 to 18,282,161, forward strand). Ensembl gene ENSG00000267959.
Homologues: Orthologues: chimpanzee MIR3188 (100% identical).